CCND1 (cyclin D1)
Diseases named in the same sentence as CCND1 in open-access papers (continued):
Sharing a sentence is not in itself a finding about the gene and the disease.
endometrial cancer (continued). "Specifically for endometrial cancer, numerous studies have reported increased cellular proliferation co-existing with progressive derailment of cyclin D1, leading to the progression of hyperplasia to endometrial endometriod carcinoma." (PMID 18822177, 2008). "Cyclin D1 is known to be upregulated in endometrial cancer and is a common feature of endometrial carcinogenesis." (PMID 16569247, 2006). "We analysed p16 gene alteration and p16, cyclin-dependent kinase 4 (CDK4), CDK6, cyclin D1, cyclin D2, cyclin D3 and retinoblastoma protein (pRb) expression in ten normal endometriums (PE), 18 endometrial hyperplasias (EH) and 35 endometrial cancers (EC)." (PMID 10682682, 2000). "Three genes (Decorin, TIMP3 and Cyclin D1) were identified to be differentially expressed between the benign endometrial tissue sample and the endometrial carcinoma samples (tissue and cell-lines)." (PMID 10901378, 2000). "Therefore, further studies on larger, independent cohorts with complete and prospectively collected data are warranted to confirm our observations and better understand the molecular mechanisms related to CCND1 in endometrial cancer." (PMID 39940659, 2025). "The discrepancy between CCND1 protein and mRNA survival trends in endometrial cancer may result from post-transcriptional regulation, including mRNA stability controlled by microRNAs or RNA-binding proteins." (PMID 39940659, 2025). "Additionally, CCND1 mRNA expression showed borderline statistical relevance for overall survival in the general endometrial cancer cohort (p = 0.029), indicating a limited prognostic value across all subtypes." (PMID 39940659, 2025). "Moreover, it is known that endometrial carcinoma cells treated with tamoxifen increase cyclin D1 expression." (PMID 38004441, 2023). "The abnormal expression of FBXL16 facilitated the MPA resistance of endometrial cancer by stabling the cyclin D1 protein; however, the proteasome-dependent degradation of cyclin D1 recognized by ubiquitinated E3 ligase was not the only one mechanism of MPA resistance." (PMID 36106050, 2022). "CCND1 expression is positively correlated with that of Ki67, which is a widely known marker of endometrial proliferation and can be used as a marker for endometrial cancer cell proliferation." (PMID 35409214, 2022). "Furthermore, FBXL16 promoted the MPA resistance of Ishikawa cells by interacting with PP2AB55α and enhancing the stability of cyclin D1 in endometrial carcinoma." (PMID 36106050, 2022). "Silencing of TICRR and PPIF led to enhance the expression of epithelial marker E-cadherin and decrease the mesenchymal marker N-cadherin and metastasis associated genes MMP9 as well as proliferation-related marker CCND1, suggesting their involvement in the progression of endometrial cancer." (PMID 33495413, 2021). "Furthermore, the stimulus of endometrial carcinoma cell lines with visfatin for 24 h induced the expression of cyclin D1, which was reduced following FK866." (PMID 33803113, 2021). "More specifically, CCND1 overexpression has been reported in many endometrial carcinomas." (PMID 30835748, 2019). "Two cases demonstrated mutation at amino acid P287 (P287S and P287T), while a third case contained a 12-bp in-frame deletion that eliminated amino acids 289–292, all of which resulted in cyclin D1 nuclear expression in more than 50% of endometrial cancer cells." (PMID 29969496, 2018). "Endometrial cancer may also be triggered through the transcriptional regulation of CCND1, the target gene of the β-catenin/Tcf-4 complex, through H3K36 methylation and activation of the WNT signaling pathway." (PMID 30057548, 2018). "Overexpression of lncRNA ABHD11‐AS1 promoted the proliferation, G1‐S progression, invasion and migration of endometrial cancer cells; inhibited apoptosis; up‐regulated cyclin D1, CDK1, CDK2, CDK4, Bcl‐xl and VEGFA; and down‐regulated p16, while ABHD11‐AS1 down‐regulation has the opposite effect." (PMID 29799152, 2018).
endometrial cancer (continued). "C-terminal CCND1 mutations across other non-endometrial carcinoma and non-mantle cell lymphoma cancer types." (PMID 29969496, 2018). "LncRNA ABHD11-AS1 promotes the development of endometrial carcinoma by targeting cyclin D1." (PMID 30402135, 2018). "Cyclin D1, a D-type cyclin regulating G1-phase cell-cycle progression, has been identified as a critical downstream effector of estrogen signaling and is frequently overexpressed in endometrial cancer." (PMID 28978098, 2017). "However, it is interesting to note that Icaritin (10 μM) induces apoptotic cell death in human endometrial cancer Hec1A cells, with marked decrease of Cyclin D1 and increase of p21 and p27 expression." (PMID 28091581, 2017). "E2 activates the PKCδ/ERK pathway and enhances cyclin D1/cdk4 expression via the membrane-initiated signaling pathways mediated by ER-α36, suggesting a possible involvement of ER-α36 in E2-dependent growth-promoting effects in endometrial cancer cells." (PMID 21079811, 2010). "One of the products, cyclin D1, which regulates the G1/S transition during the cell cycle, and the other, c-Myc, which acts as an important proto-oncogene, have both been found to be highly expressed in endometrial carcinoma and are positively correlated with tumor stage and survival 40-42." (PMID 36035375, 2022). "Since cyclin D1 can be an alternative target of therapy and small-molecule inhibitors for the Pak family are being developed, combined-targeted therapy may be achieved for targeting endometrial cancer." (PMID 26218748, 2015). "Next, we analyzed the relationship between RCOR2 and the proliferation-related genes MKI67, CCND1, and PCNA under the mRNA levels, in endometrial cancer." (PMID 40936699, 2025). "Correlation analysis showed that all three genes, MKI67, CCND1, and PCNA, exhibited a significant positive correlation with RCOR2 mRNA expression in endometrial cancer tissues." (PMID 40936699, 2025). "Our work revealed that the abnormal expression of FBXL16 in Ishikawa cells led to the inhibition of GSK3β-dependent cyclin D1 degradation and ultimately the promotion of MPA resistance in endometrial carcinoma." (PMID 36106050, 2022). "Our study showed similar results, where hinokitiol treatment for 48 h significantly reduced the expression of cyclin D1 and CDK4 in endometrial cancer cells." (PMID 34361036, 2021). "Positive correlations are identified between cyclin D1 and autophagy markers Beclin1 and ATG5, suggesting cyclin D1-mediated autophagy activation may facilitate lymph node metastasis in endometrial cancer." (PMID 41209546, 2025). "Moreover, the qPCR results of proliferation-related genes, MKI67, CCND1, and PCNA, supported the regulatory effects of ROCR2 on endometrial cancer cell proliferation." (PMID 40936699, 2025). "Additionally, hUCMSC-EVs were found to inhibit the proliferation and migration of endometrial cancer cells by transferring miRNA-302a and downregulating the AKT signaling pathway and cyclin D1." (PMID 39063032, 2024). "Furthermore, we looked into the interaction of AM and 4-OH-TMX on the gene expression of CCND1 and MKI-67 in stromal endometrial cells, since several studies have proposed these genes as potential biomarkers for endometrial cancer development." (PMID 38004441, 2023). "CCND1 is highly expressed in the proliferative and secretory phases of the menstrual cycle in the uterus, and its high expression level in endometrial cancer is observed in metastatic rather than non-metastatic carcinomas." (PMID 35409214, 2022). "Importantly, our data showed that engineered extracellular vesicles rich in miR-302 significantly inhibited the expression of cyclin D1 and suppressed AKT signaling pathway in endometrial cancer cells." (PMID 31001342, 2019).
endometrial cancer (continued). "After overexpressed of miR-490-3p in endometrial cancer cells the expression of TGFα was decreased, while EGFR and the downstream related genes including NF-kB, MMP-2, Cyclin D1, survivin were decreased in mRNA and protein level, while increased Bax expression." (PMID 26843615, 2016). "Functionally, knockdown of Pak1, but not Pak4, in endometrial cancer cell line led to reduced cell proliferation along with reduced cyclin D1, estrogen receptor (ERα) and progestogen receptor (PR) expression." (PMID 26218748, 2015). "Our discovery that the expression of both cyclin D1 and MMP7 was higher in endometrial tumors than in normal, non-cancerous endometrium is consistent with previous reports showing that both of these proteins are elevated in patients with endometrial cancer." (PMID 22792274, 2012). "One report showed that 50% (7/14) of endometrial carcinomas had cyclin D1 overexpression and that there was no immunopositive difference between these carcinomas and simple hyperplasia which is a precursor for endometrial cancer development." (PMID 18822177, 2008). "A previous study showed that SOX7 might be a negative regulator of Wnt/β-catenin signaling pathway through disrupting the transcriptional activity of β-catenin–TCF/LEF complex and its downstream targets, such as Cyclin D1, c-Myc, and FGF9 in endometrial cancer." (PMID 29029454, 2017). "Besides, AZD1080 exposure decreased NF-kB, Cyclin D1 and MMP9 expression while increased P21 expression, thus we guess that AZD1080 may be an effective drug for treating endometrial carcinoma." (PMID 27050373, 2016). "However, addition of PGE2 counteracted the impact of ω-3 PUFAs on Akt phosphorylation and cyclin D1 expression, suggesting that regulation of COX-2 expression and PGE2 production played a major role in ω-3 PUFAs-mediated growth inhibition of endometrial cancer." (PMID 26468779, 2015). "Furthermore, WB showed that RCOR2 knockdown or overexpression could change the expression of MKI67, CCND1, and PCNA in endometrial cancer cells remarkedly, which further demonstrated at the protein level that RCOR2 the proliferation of endometrial cancer cells." (PMID 40936699, 2025). "Thus, metformin might promote a hyperactive state of GSK3-β in endometrial cancer cells, resulting in a further decrease in β-catenin protein and a drop in the transcription of TCF/LEF target genes, including the cell-cycle regulatory genes cyclin D1 and c-myc." (PMID 33946426, 2021).
esophageal cancer (78 papers, 1995 to 2025). A primary or metastatic malignant neoplasm involving the esophagus. "Cyclin D1 is a therapeutic target for esophageal cancer, and the nanoparticles exerted selectivity, causing a significant decrease in cyclin D1 expression in the KYSE30 cells, while in the normal cells it was at least 2-fold higher." (PMID 41155703, 2025). "The overexpression of cyclin D1 is often associated with the worst clinical outcomes and prognosis in patients with esophageal cancer." (PMID 38464761, 2024). "For instance, miR-93-5p transferred by exosomes can promote the proliferation of recipient esophageal cancer cells and affect the expression of PTEN and its downstream proteins p21 and cyclin D1, enhancing the clinical risk of esophageal cancer." (PMID 30925927, 2019). "One meta-analysis exhibited the statistically significant association between CCND1 G870A polymorphism and a risk for cancers of the digestive tract, including esophageal cancer." (PMID 23675381, 2013). "The CCND1 A870A genotype is statistically reliable to determine its susceptibility to esophageal cancer (OR = 2.82, p = 0.004)." (PMID 23675381, 2013). "Mutations of the CCND1 gene disrupting the phosphorylation at Thr286 and thereby leading to nuclear accumulation of cyclin D1 have been described in endometrial and esophageal carcinomas further reinforcing this notion." (PMID 20459741, 2010). "Sequencing of cyclin D1 (CCND1) in a panel of 90 patient esophageal carcinomas revealed mutation of Thr-286 to arginine and a deletion of C-terminal residues 266–295." (PMID 18764945, 2008). "Additionally, a significant association between CCND1 polymorphism and increased risk for breast and esophageal cancer has been established." (PMID 30361291, 2018). "Lastly, esophageal cancer often exhibits intrachromosomal amplification of MYC, ERBB2, EGFR, RB1, GATA4/6, CCND1, RTK and MDM2 as well as ecDNA-associated amplification of MYC and MDM2." (PMID 41415205, 2025). "Cyclin D1 is produced in more significant amounts when the CCND1 gene is amplified in esophageal cancer, which promotes tumor growth by accelerating cell division." (PMID 40563418, 2025). "Cyclin D1 controls the cell cycle entry from the G1 to the S phase and is overexpressed in many human cancers, including esophageal cancer." (PMID 38464761, 2024). "Previous studies have shown that a significant difference for cyclin D1 expression was found between esophageal carcinomas and the adjacent epithelia and inhibiting cyclin D1 can enhance the radiosensitivity of esophageal cancer cells." (PMID 35484963, 2022). "Esophageal Cancer: curcumin modulated Notch-1 signaling and suppressed NF-jB and its downstream targets involving Bcl2, cyclin D1, VEGF, and MMP-9 in oral squamous cell carcinomas." (PMID 36712505, 2022). "For example, approximately 45% of driver events in esophageal cancer included focal amplifications in cell cycle genes such as CCND1/2/3 and CDK4/6/9, in addition to amplifications in ERBB2, KRAS, MYC." (PMID 33889297, 2021). "Knockdown of ATP-dependent RNA helicase inhibited the expression of β-catenin, c-Myc, and cyclin D1 in esophageal cancer cells through suppressing the Wnt/β-catenin signaling pathway." (PMID 32903837, 2020). "The results showed a significant correlation between the expression levels of SPINK5 and β‐catenin (CTNNB1), LRP5, LRP6, DVL3, LEF1, AXIN2, MYC, and cyclin D1 (CCND1) in esophageal cancer." (PMID 30868765, 2019).
esophageal cancer (continued). "Intron 4-retaining CCDN1 expressed in prostate and esophageal cancers was found to translate into a truncated cyclin D1 protein which has oncogenic effects." (PMID 29535836, 2018). "For example, Intron 4-retaining CCDN1 (cyclinD1) expressed in prostate and esophageal cancers was found to translate into a truncated cyclin D1 protein, which has oncogenic effects." (PMID 29143801, 2017). "Data of 416 cases from the Research Committee on Malignancy of Esophageal Cancer, Japanese Society for Esophageal Diseases showed that increased cyclin D1 expression was a significant prognostic factor that decreased OS in patients with ESCC." (PMID 27145270, 2016). "In patients with esophageal cancer, many prognostic markers, including cyclin D1, E-cadherin, and MDM2, have been reported." (PMID 28536608, 2016). "The expression of cyclooxygenases-2 (COX-2) and Cyclin D1 in rat esophageal tissues and the esophageal cancer cells were also significantly reduced by RPS (all P < 0.01)." (PMID 26147856, 2015). "It has been shown that the expression of cyclin D1, p21 and p27 is involved in the occurrence of esophageal cancer, and p21 and p27 have been proposed as candidate tumor suppressor genes." (PMID 24348764, 2014). "Substantial prevalence of CCND1 A870A homozygous has been detected in the esophageal cancer case cohort (38 versus 18% in control)." (PMID 23675381, 2013). "Regarding over-expression, moderate and slight poor agreement of Cyclin D1 and Her-2/neu protein expression with gene positioning was also observed in esophageal carcinoma (Kappa = 0.444; p = 0.091 and Kappa = 0.194; p = 0.301, respectively)." (PMID 21637674, 2009). "In another study β-catenin and cyclin D1 expression was correlated with survival of esophageal cancer patients." (PMID 17309796, 2007). "Oncogenic mutations of CCND1 have been previously reported in endometrial and esophageal carcinomas, however, the spectrum of CCND1 mutations across human cancers has not been systematically investigated." (PMID 29969496, 2018). "Cyclin D1 is an important protein for the G1-S cell cycle phase transition that participates in cell proliferation and differentiation, and has been demonstrated to promote the progression of several human tumor types, including esophageal cancer." (PMID 27145270, 2016). "In addition, the expression of Cyclin D1 in the esophageal cancer cells was markedly reduced by RPS treatment." (PMID 26147856, 2015). "Consistent with reports that identified c-MYC and Cyclin D1 as two important targets of the β-catenin/TCF transcription complex, our results demonstrated that t-DARPP-mediated activation of β-catenin/TCF leads to up-regulation of c-MYC and Cyclin D1 in gastric and esophageal cancer cells." (PMID 21447180, 2011). "Significantly, recent assessment of the Fbx4 sequence in primary esophageal carcinoma samples identified hemizygous, missense mutations in 14 percent of the tumors; no mutations occurred in αB crystallin or CCND1 genes in tumors expressing mutated Fbx4." (PMID 18764945, 2008). "It has been reported that immunohistochemical examination of cyclin D1 expression may provide important prognostic information for esophageal cancer." (PMID 17309796, 2007). "All the cases showing nuclear localization of β-catenin protein overexpressed cyclin D1 which may have contributed to the oncogenesis of the esophageal carcinoma." (PMID 17309796, 2007). "We also found that the copy number amplification of CCND1 in esophageal cancer was significantly more frequent than that in esophageal mucosa, consistent with the notion that CCND1 amplification is a common genetic aberration in ESCC and may promote tumor cell proliferation." (PMID 35515115, 2022).